APOE (apolipoprotein E)
Diseases named in the same sentence as APOE in open-access papers (continued):
Sharing a sentence is not in itself a finding about the gene and the disease.
dyslipidemia (continued). "The difference in the proportion of probands with a high probability of polygenic dyslipidemia was more marked in the ADH cohort (61% for APOE variant carriers vs. 46%)." (PMID 35628605, 2022). "The TG, TC, LDL-c, and LDL/HDL ratio indices were elevated in the EKO CD group compared with the WT CD group due to ApoE knockout-associated dyslipidemia." (PMID 35172845, 2022). "Correlation between allelic and genotypic frequencies of APOE polymorphisms versus the risk of dyslipidemia served as a key attraction to conduct this study." (PMID 35573533, 2022). "Our results reveal an independent association between APOE rs429358 genotypes and metabolic syndrome." (PMID 36011277, 2022). "The VUS and LB APOE variants were observed more frequently in probands with a high probability of polygenic dyslipidemia compared to the P/LP and VUS/P,LP variants." (PMID 35628605, 2022). "APOE variants have been reported in different types of dyslipidemias, such as autosomal-dominant hypercholesterolemia, familial combined hyperlipidemia, familial dysbetalipoproteinemia, and lipoprotein glomerulopathy." (PMID 36011277, 2022). "In this study, we evaluated the effects of the daily consumption of TIMEx on the dyslipidemia of atherosclerotic mice (apolipoprotein E-deficient mice; ApoE−/− mice) that were consuming a 20% fat-containing diet." (PMID 35208189, 2022). "The APOE ε2 allele appears to be associated with abdominal obesity, insulin resistance, and metabolic syndrome in a group of women from southwest China who have PCOS." (PMID 36406137, 2022). "A further plausible mechanism, given that APOE ε4 predisposes to metabolic syndrome and increased insulin resistance would be through secondary increased obesity; however, ε4 carriers on average have a lower body mass index than do ε3 or ε2 carriers." (PMID 35354468, 2022). "Our data also provide evidence for the association of APOE locus variants with metabolic syndrome and serum albumin levels." (PMID 36011277, 2022). "In this study, we evaluated the effects of daily consumption of a hot-water extract of thinned immature mango fruits (TIMEx) on the dyslipidemia of apolipoprotein E-deficient (ApoE−/−) mice." (PMID 35208189, 2022). "Stepwise logistic regression analysis demonstrated that APOE rs429358 is independently associated with metabolic syndrome (odds ratio: 1.20 for each C-allele, 95% confidence interval: 1.15–1.26, p = 2.29 × 10−14)." (PMID 36011277, 2022). "We investigated the associations between genetic variants around the APOE locus, cardiometabolic traits, and metabolic syndrome in a Taiwanese population." (PMID 36011277, 2022). "The proportion of probands with a high probability of polygenic dyslipidemia was increased in the cohort of APOE variant carriers (55% vs. 46%), whereas the probability of monogenic dyslipidemia was similar (20% vs. 22%)." (PMID 35628605, 2022). "The dyslipidemia caused by ApoE knockout in the ApoE CD, ApoE WD, and ApoE WD EX groups significantly reduced the total SCFAs and propionate and butyrate levels, as compared with the WT CD group." (PMID 35256637, 2022). "Recently, COVID-19 has been also linked to dyslipidemia associated with deficiency of apolipoprotein E (ApoE)." (PMID 33717168, 2021). "Especially, Apolipoprotein E4 (APOE4), the strongest genetic risk factor for late onset AD, was also associated with metabolic syndrome." (PMID 33407809, 2021). "Past studies have shown that women are less likely to be treated with statin therapy, and as APOE ε4 carriers have increased risk for dyslipidemia; this likely increases the likelihood of patients with this genotype to be treated with statins." (PMID 33969178, 2021). "Nevertheless, the observed link between AD and the apolipoprotein E4 (ApoE4) allele also points to a role of dyslipidemia in the pathogenesis of AD." (PMID 34502369, 2021). "Several studies suggested a direct link between Cu deficiency and dyslipidemia with increased concentrations of ApoE." (PMID 32155648, 2020).
dyslipidemia (continued). "In humans and APOE-TR mice, the APOE4 allele is associated with lower BMI but greater aspects of the metabolic syndrome manifested in elevated plasma glucose and insulin, particularly in obese APOE4 carriers." (PMID 32587511, 2020). "When compared to wild type C57BL/6 mice fed a high caloric diet, ApoE KO mice are more susceptible to developing states of dyslipidemia, hepatic steatosis, and steatohepatitis." (PMID 32796650, 2020). "Three APOE gene variants—ɛ2, ɛ3, and ɛ4—are investigated with regard to the risks of cardiovascular diseases and metabolic disorders, including dyslipidemia and insulin resistance." (PMID 32630105, 2020). "A high-fat diet-induced model and ApoE−/− transgenic mice are commonly used as animal models to investigate dyslipidemia-associated metabolic disorders." (PMID 31936037, 2020). "A multivariate analysis showed that age at baseline, ApoE e4 and dyslipidemia increase the risk of progression to AD." (PMID 32485802, 2020). "In C57BL/6 mice, adenovirus-mediated gene transfer of this dominant negative mutant (c-Jun DN), lacking a major part of the transactivation domain, had induced hepatic apoE overexpression, which caused dyslipidemia." (PMID 30909560, 2019). "In this study, we investigated the association between two common ApoE polymorphisms (rs7412 and rs429358) and baseline lipid profiles and statins response in dyslipidemia ASCVD patients classified with clinical E2/3/4 phenotypes." (PMID 31153375, 2019). "APOE-deficient mice were found to develop metabolic syndromes, non-alcoholic steatohepatitis and liver fibrosis after being fed a cholesterol and fat rich diet or a methionine-choline-deficient-diet (MCD)." (PMID 30589872, 2018). "Here we show that cordycepin (Cpn), a natural derivative of adenosine, markedly reduced atherosclerotic plaque and ameliorated associated symptoms such as dyslipidemia, hyperglycemia and inflammation in ApoE-/- mice." (PMID 29212261, 2017). "Although several studies have reported an association between APOE polymorphism and obesity, insulin resistance and the metabolic syndrome, the results are inconsistent." (PMID 28727855, 2017). "We have examined the possible association of the APOE rs429358 and rs7412 polymorphism with lipid profiles and disorders in 600 normal and 249 dyslipidemia children." (PMID 27724906, 2016). "The ε3 (112 cysteine-Cys, 158 arginine-Arg) allele is considered the “neutral” APOE genotype while the ε4 (112 Arg and 158 Arg) and ε2 (112 Cys, 158 Cys) allele associated with dyslipidemia in different adult populations." (PMID 27724906, 2016). "We have not yet considered the influence of diet and physical activity to the association of the APOE polymorphism with dyslipidemia in Vietnamese children." (PMID 27724906, 2016). "In this paper, we report our findings from a large cross-sectional study on the association between selenium levels and the risk of dyslipidemia controlling for APOE genotype in this elderly Chinese sample." (PMID 26380972, 2015). "The aim of the present study was to investigate the correlation between apolipoprotein E (ApoE) gene polymorphisms and the occurrence of urolithiasis and dyslipidemia." (PMID 25452799, 2015). "Although associations between selenium level and APOE genotype were found in population based studies, we found an independent association of selenium and APOE on the risk of dyslipidemia in the present study." (PMID 26380972, 2015). "Adipocyte expansion, WAT inflammation and ectopic lipid accumulation are highly associated with the pathogenesis of metabolic syndrome, and are likely critical to the observed insulin resistance phenotype in Eln +/−;ApoE −/− mice." (PMID 26167199, 2014). "We confirm that human schistosomiasis causes dyslipidemia and report for the first time that certain changes in plasma lipid and lipoprotein levels depend on APOE gene polymorphism." (PMID 25051269, 2014).
dyslipidemia (continued). "In apoE−/− mice, dyslipidemia-related kidney injury is associated with remarkable pathological alterations, including lipid deposition at the glomerulus, an expanded meangium, and an accumulated extracellular matrix (ECM)." (PMID 24972137, 2014). "In summary, we confirm that human schistosomiasis causes dyslipidemia and, for the first time, report that certain changes in plasma lipid levels and lipoprotein profiles are dependent on patient APOE gene polymorphism." (PMID 25051269, 2014). "In ApoE deficient mice, a Western-like diet induces a massive dyslipidemia and the circulating levels of cholesterol and TGs mainly reflect the contribution from the intestine." (PMID 24324578, 2013). "Some studies show that variants of apo A-V and C-III, interacting with APOE genotypes, are associated with the severity of antiretroviral treatment-induced dyslipidemia." (PMID 21939545, 2011). "In the present study, we used the genetically modified apolipoprotein E deficient (ApoE−/−) mouse, a widely used mouse model of atherosclerosis and natural hypercholesterolemia, to study the effect of dyslipidemia on endothelial VCAM-1 expression." (PMID 20856927, 2010). "The elevated susceptibility of the ApoE-/- mice is important because these mice at young age display a modest dyslipidemia with elevated levels of cholesterol in plasma." (PMID 19138394, 2009). "Earlier studies in T2DM patients have shown that ε2 and ε4 alleles of APOE are associated with high risk for dyslipidemia, nephropathy, retinopathy, and coronary artery disease but other studies have shown contradictory results." (PMID 15992403, 2005). "In contrast to APOE ε4-associated dyslipidemia, APOE2 carriers tend to have high triglyceride levels, and up to 10% of APOE2 homozygotes have familial dysbetalipoproteinemia, an atherogenic disorder characterized by an accumulation of triglyceride-rich lipoprotein remnants." (PMID 39364911, 2025). "We hypothesize that APOE genotypes influence DPN risk via glycemia-independent dyslipidemia pathways, though our cross-sectional design limits inference on temporal links between genotype, lipid alterations, and neuropathy onset." (PMID 41488146, 2025). "In addition, polymorphism of APOE ε4 which involved in lipid metabolism is associated with risk of metabolic syndrome." (PMID 40379890, 2025). "Despite being the main regulator of whole-body cholesterol and lipoprotein homeostasis, the hepatic contribution to DMD-associated dyslipidemia and exacerbation of muscle wasting in mdx-ApoE mice is unknown." (PMID 39716324, 2024). "Oral sulforaphane (5 to 15 mg/kg) treatment in ApoE-deficient (ApoE − / −) mice that were fed a high-fat diet resulted in the amelioration of dyslipidemia, the formation of atherosclerotic plaques, and the unstable phenotype, which is known to be a risk factor for AD." (PMID 39493676, 2024). "Another study in apolipoprotein E-deficient (ApoE−/−) mice showed that dyslipidemia impairs the innate immune response to P. gingivalis challenge, which may contribute to the increased activity of this species." (PMID 39850469, 2024). "Age, female sex, traumatic brain injury, depression, environmental pollution, physical inactivity, social isolation, low academic level, metabolic syndrome, and genetic susceptibility—primarily mutations in the ε4 allele of apolipoprotein E (APOE, 19q13.32)—are the main risk factors of sporadic AD." (PMID 39200803, 2024). "These include female sex, traumatic brain injury, depression, environmental pollution, physical inactivity, social isolation, low academic level, metabolic syndrome, and genetic susceptibility, particularly mutations in the ε4 allele of apolipoprotein E (APOE) located on chromosome 19q13.32." (PMID 39000382, 2024). "Recent studies have demonstrated that ponatinib could improve dyslipidemia and atherosclerotic plaque formation in apolipoprotein E-deficient mice, suggesting that ponatinib exerted a significant role in lipid metabolism." (PMID 39840105, 2024).
dyslipidemia (continued). "Studies have indicated that apoE deficient animals could spontaneously develop severe dyslipidemia and liver steatosis." (PMID 37641103, 2023). "In addition to its potent risk-modifying effect on AD44, ApoE plays a key role in cholesterol metabolism in the periphery, with the APOE ε4 allele associated with dyslipidemia and coronary heart disease." (PMID 36909654, 2023). "Therefore, ApoE_rs429358 is associated with dyslipidemia, indicating it impacts ApoE activity, thereby modulating the lipid profile." (PMID 37860035, 2023). "Additionally, there was a significant risk of dyslipidemia for APOE ε4 carriers (OR = 1.804; p = 0.036), whereas BIN1 rs744373 risk-allele carriers were at a significantly lower risk of having dyslipidemia (OR = 0.558; p = 0.006)." (PMID 39081475, 2022). "Elevated LDL-C may thus have been due to a major effect of the inherited pathogenic APOE variant or a variant in an unidentified gene linked to dyslipidemia." (PMID 35628605, 2022). "RAP could theoretically cause dyslipidemia, while ApoE−/- mice may also have lipid abnormalities during a high-fat diet." (PMID 35350774, 2022). "Thus, additional studies are required to elucidate the role of APOE variants, especially rs429358, in the risk of metabolic syndrome." (PMID 36011277, 2022). "Additionally, rs9804646 in the APOA5 gene, as well as rs56156922 and rs429358 in the APOE gene, were associated with dyslipidemia." (PMID 36419087, 2022). "In PWH mild alterations in the CDT could be an early signal of cerebrovascular damage, especially in patients carrying APOE variant correlated with dyslipidemia." (PMID 35353274, 2022). "The carrier of APOE ε2 could be a protective factor of dyslipidemia, while APOE ε4 carriers might be closely associated with the high TG, particularly in elderly females." (PMID 34749748, 2021). "Finally, according to the 2016 China dyslipidemia criteria, using the logistic regression models, we found that, for 40+ males and 65+ males, the APOE ε2 carriers were less likely to have at-risk levels of high LDL-C (≥ 3.4 m mol/L)." (PMID 34749748, 2021). "We hypothesized that the APOE genotype would influence metabolic syndrome risk markers, both at baseline and in response to intake of the different meals." (PMID 34836179, 2021). "Finally, a multivariate logistic regression model was used to evaluate the associations between the APOE allele carriers and the at-risk levels of dyslipidemia." (PMID 34749748, 2021). "It has been therefore suggested that deficiency in ApoE found in SARS-CoV2 dyslipidemia may be linked to disease progression and complications." (PMID 33717168, 2021). "For that reason, this study was conducted in ApoE-/- mice, which have a genetic predisposition to develop chronic inflammation, including metabolic syndrome as a useful tool to explore the therapeutic effects of a novel selective NLRP3 antagonist in lean NAFLD." (PMID 34513923, 2021). "Taking these findings together, we could speculate that apoE genotypes may predict the risk for dyslipidemia and CVD in the RA cohort." (PMID 33297350, 2020). "Taken together, these data suggest that ApoE−/− mice are an appropriate model for studying light-induced circadian disruption and that exacerbated dyslipidemia may mediate atherosclerotic lesion formation caused by constant light exposure." (PMID 32555251, 2020). "Several studies have been conducted in APOE mice on the effects of HFDs, because clinical studies showed APOE4-positive individuals have increased risk of metabolic syndrome and obese APOE4 carriers have increased metabolic disturbances when compared to APOE3 carriers." (PMID 31554665, 2019). "Thus, our results suggest that APOE gene variants affect risk of dyslipidemia in individuals who carry the E4 risk allele and GG genotype at SNP rs445925." (PMID 29712557, 2018). "Metabolic markers associated with the Metabolic Syndrome (MetS) may be affected by interactions between the APOE genotype and plasma fatty acids (FA)." (PMID 28740125, 2017).